TAGLN (transgelin)
Diseases named in the same sentence as TAGLN in open-access papers (continued):
Sharing a sentence is not in itself a finding about the gene and the disease.
cardiomyopathy (2 papers, 2022 to 2023). A disease of the heart muscle or myocardium proper. "The upregulation of TAGLN in the heart of rats with ISO-iCM implicates its participation in cardiomyopathy by functioning as smooth muscle protein." (PMID 36034815, 2022).
cholangiocarcinoma (2 papers, 2024). A carcinoma that arises from the intrahepatic biliary tree (intrahepatic cholangiocarcinoma) or from the junction, or adjacent to the junction, of the right and left hepatic ducts (hilar cholangiocarcinoma). "Consequently, these images demonstrated that at the invasive margin in replacing HGP, Keratin 7-positive cholangiocarcinoma cells were closely opposed to CD34-positive sinusoid-like vessels (vessel co-option) in addition to TAGLN-positive tumoral vessels." (PMID 38960952, 2024). "Mechanistic studies revealed that TAGLN promotes cell proliferation, migration, and tumor formation by regulating the cytoskeleton and activates the oncogenic p38 MAPK pathway in CRC and cholangiocarcinoma." (PMID 39335106, 2024). "The ectopic expression of an actin-binding protein, Transgelin (TAGLN), promotes CRC and cholangiocarcinoma by enhancing stem cell programs." (PMID 39335106, 2024).
chronic kidney disease (2 papers, 2024). Impairment of the renal function secondary to chronic kidney damage persisting for three or more months. "Although further validation in a large cohort is necessary, the potential use of TAGLN as a biomarker for kidney fibrosis has been reported in Chronic Renal Insufficiency Cohort (CRIC) study that used human plasma proteome data." (PMID 39375532, 2024). "In individuals with MM, serum transgelin, U IGFBP-7/creatinine and U TIMP2/creatinine ratios may have utility as biomarkers of predicting advanced chronic kidney disease stages." (PMID 38708150, 2024).
COVID-19 (2 papers, 2022 to 2024). A disease caused by infection with severe acute respiratory syndrome coronavirus 2. "The expression of serum transgelin is positively with the severity and poorly prognostic outcomes among COVID-19 patients, indicating that transgelin is implicated in the pathological process of COVID-19." (PMID 39676863, 2024). "The expression of serum transgelin on admission was gradually elevated in parallel with the increased severity scores of COVID-19." (PMID 39676863, 2024). "Correlative analyses found that serum transgelin expression was strongly related to the levels of many clinical parameters in COVID-19 patients." (PMID 39676863, 2024). "Collectively, all of these outcomes indicated that serum transgelin expression on admission can indicate the severity of COVID-19." (PMID 39676863, 2024). "The data indicated that the expression of serum transgelin was ascended in line with COVID-19 severity scores." (PMID 39676863, 2024). "In the current investigation, serum transgelin was detected for the first time among COVID-19 patients." (PMID 39676863, 2024). "Further analyses demonstrated that serum transgelin expression on admission was positively related to the adversely prognostic risks in COVID-19 patients." (PMID 39676863, 2024). "Assessing the relationships of serum transgelin expression with severity and outcomes are beneficial to illuminate the role of transgelin in COVID-19 patients." (PMID 39676863, 2024). "Serum transgelin expression was substantially decreased in the same COVID-19 patients during the convalescent phase after treatment." (PMID 39676863, 2024). "Transgelin knockout should be executed, and the effect of transgelin knockout on the process was needed to conduct in mice model of COVID-19." (PMID 39676863, 2024). "In the present study, serum transgelin expression on admission was increased in parallel with COVID-19 severity scores." (PMID 39676863, 2024). "The evidences above revealed that transgelin may involve in the progression of COVID-19, supporting its probable usefulness as a serum biomarker for estimating illness state and prognosis of COVID-19 patients." (PMID 39676863, 2024). "Moreover, in the basis of CURXO score, serum transgelin expression was obviously upregulated in the severe COVID-19 patients." (PMID 39676863, 2024). "This study found a potential role of transgelin in COVID-19 patients." (PMID 39676863, 2024). "Besides, positive associations between serum transgelin with interleukin-6 (IL-6), CRP, D-Dimer, and lactate dehydrogenase (LDH) were observed among COVID-19 patients." (PMID 39676863, 2024). "Based on A-DROP score, serum transgelin expression was the highest in critical COVID-19 cases." (PMID 39676863, 2024). "TAGLN is a typical EMT marker gene that is elevated in COVID-19 patients." (PMID 36248845, 2022). "However, the expression and change of transgelin are unclear in patients with COVID-19." (PMID 39676863, 2024). "In addition, we found that serum transgelin was the highest in the highest scores of MuLBSTA, PSI, CURB-65, and COVID-GRAM among COVID-19 patients." (PMID 39676863, 2024). "The specific role of transgelin in the progression of COVID-19 was not explored in this research." (PMID 39676863, 2024).
glioblastoma (2 papers, 2012 to 2024). The most malignant astrocytic tumor (WHO grade IV). "Importantly, both TAGLN and TES have been characterized as tumor suppressors in malignancies outside the brain and the latter is often silenced by promoter hypermethylation in glioblastoma." (PMID 23046790, 2012). "Similarly, TAGLN and TES were absent or low in most GNS cell lines, but displayed the opposite trend in glioblastoma tissue compared to normal brain or grade III astrocytoma." (PMID 23046790, 2012).
heart failure (2 papers, 2013 to 2023). Inability of the heart to pump blood at an adequate rate to meet tissue metabolic requirements. "However, only SDSL showed an AUC value greater than 0.7 in the test set, whereas EGFL7, SMTNL2, MFAP4, TAGLN, SGPP2 and SMTNL2 showed AUC values greater than 0.5, so SDSL may be a high risk factor in patients with heart failure." (PMID 38250028, 2023). "The analysis revealed that heart failure samples had significantly higher expression levels of EGFL7, SDSL, PPP1R13l, SMTNL2, MFAP4, and TAGLN genes, which may promote the development of heart failure." (PMID 38250028, 2023).
kidney injury (2 papers, 2024). Trauma to the kidney. "Additionally, our H2O2-induced cellular model suggested that the utility of TAGLN could be extended to acute kidney injury." (PMID 39375532, 2024).
leukaemia (2 papers, 2021 to 2024). "Further, transgelin is reportedly up-regulated in leukaemia and lymphoma cells." (PMID 38708150, 2024). "Several studies revealed transgelin upregulation in leukemia and lymphoma cell lines." (PMID 35011306, 2021).
Multiple Myeloma (2 papers, 2021 to 2024). "The study’s objective was to evaluate the utility of urinary IGFBP-7, urinary TIMP-2, and serum transgelin levels as biomarkers for the prediction of renal impairment in patents with multiple myeloma." (PMID 38708150, 2024).
nephritis (2 papers, 2013 to 2021). Inflammation of renal tissue. "The increasing expression of transgelin was repeatedly detected in podocytes, parietal, and tubular cells during initiation of nephritis and various types of nephropathies and in the mesenchymal cells of renal tumor stroma." (PMID 34572331, 2021).
nephropathies (2 papers, 2013 to 2021). "This is in agreement with our observations in human biopsy material, where we have noticed in many nephropathies of different etiology, many renal cell types over-expressing transgelin." (PMID 23840546, 2013).
neurofibroma (2 papers, 2020 to 2025). An intraneural or extraneural neoplasm arising from nerve tissues and neural sheaths. "The transgelin expression was significantly upregulated in NF1-associated MPNSTs compared to plexiform neurofibromas, and this overexpression corresponded with hypomethylation in TAGLN regulatory regions." (PMID 40843672, 2025). "A study of tumors from the same NF1 patient at the TAGLN locus found that only the MPNST lacked methylation, correlating with increased expression of transgelin, but this is in contrast to another study that found decreased expression relative to neurofibromas." (PMID 32642732, 2020).
oral cancer (2 papers, 2023 to 2024). "We further identified TAGLN as a direct target of let-7c-5p, which has been implicated in modulating the oncogenic potential of oral cancer cells." (PMID 39308508, 2024). "Our findings highlight the role of exosomal let-7c-5p in enhancing oral cancer cell aggressiveness by downregulating TAGLN expression, highlighting its potential as a diagnostic and therapeutic strategy." (PMID 39308508, 2024). "Nevertheless, this study validated the promoting role of exosomal let-7c-5p in oral cancer cells by directly targeting and downregulating TAGLN, thus providing a crucial indication for the further application and exploration of relevant agents." (PMID 39308508, 2024). "The effects of let-7c-5p and TAGLN overexpression on oral cancer cell viability, migration, and invasion were analyzed via CCK-8 and Transwell assays." (PMID 39308508, 2024). "In the context of oral cancer, our research had identified that TAGLN was downregulated in the presence of oe-let-7c-5p-exo, and overexpression of TAGLN reversed the promoting role of let-7c-5p in cancer cells." (PMID 39308508, 2024). "Our study contributes to this knowledge by suggesting that the let-7c-5p-TAGLN axis is a critical modulator of oral cancer aggressiveness." (PMID 39308508, 2024). "Differential gene expression profiles further substantiated the influence of let-7c-5p in targeting TAGLN in oral cancer pathobiology." (PMID 39308508, 2024). "In conclusion, with this study we propose that let-7c-5p is a potential biomarker for oral cancer; our results evidence the role of let-7c-5p in promoting an aggressive cancer phenotype, possibly through direct targeting and downregulation of TAGLN." (PMID 39308508, 2024). "Our findings are particularly illuminating as they suggest a novel mechanism wherein let-7c-5p may modulate oral cancer pathophysiology through the downregulation of TAGLN." (PMID 39308508, 2024). "Overexpression of TAGLN reverses the promoting role of let-7c-5p on oral cancer cells." (PMID 39308508, 2024). "The intersection of these oral cancer-related genes with our curated list of predicted and validated let-7c-5p targets resulted in three genes of interest: HOXA1, TAGLN, and TSPAN2." (PMID 39308508, 2024). "The role of TAGLN in oral cancer has not been fully elucidated, and further experiments are needed." (PMID 39308508, 2024).
serous ovarian cancer (2 papers, 2019 to 2023). "These included several upregulated proteins previously identified in high-grade serous ovarian cancer (SHMT1, TAGLN)." (PMID 38014221, 2023).
adenoma (1 paper, 2020). A neoplasm arising from the epithelium. "The expression of COMP and TAGLN significantly increased during the colorectal normal-adenoma-adenocarcinoma sequence (all p< 0.05), and patients with high expression of COMP and TAGLN had high clinical staging." (PMID 32754278, 2020).
aortic valve stenosis (1 paper, 2019). Aortic valve stenosis (AVS) is a condition characterized by narrowing of the heart's aortic valve opening. "We detected an upregulation of complement 9 (C9), serum amyloid P-component (APCS) and transgelin as well as downregulation of heat shock protein (HSP90), protein disulfide isomerase A3 (PDIA3), annexin A2 (ANXA2) and galectin-1 in patients with aortic valve stenosis." (PMID 31856737, 2019).
Apathy (1 paper, 2024). Apathy is a quantitative reduction of interest, motivation and the initiation and persistence of goal-directed behavior, where often the accompanying emotions, thoughts, and social interactions are also diminished. "The ECM module, associated strongly with agitation and psychosis and more weakly with apathy, yielded 10 potential hub genes, including TAGLN (MFC,agitation = 0.362, p = 1.3 × 10−5) and FLNA (MFC, agitation = 0.646, p = 5.9 × 10−6)." (PMID 38575567, 2024).
autosomal dominant cutis laxa (1 paper, 2024). Autosomal dominant cutis laxa (ADCL) is a connective tissue disorder characterized by wrinkled, redundant and sagging inelastic skin associated in some cases with internal organ involvement. "MYH11 and SYNPO2 linked to EMILIN1-related Connective Tissue Disease, AOC3 and MYH11 linked to Autosomal Dominant Cutis Laxa, MYH11 and SYNPO2 linked to Lethal Arteriopathy Syndrome due to Fibulin-4 Deficiency, while AOC3 and TAGLN linked to Renal Tubular Dysgenesis of Genetic Origin." (PMID 39480826, 2024).
breast ductal carcinoma (1 paper, 2022). "For instance, TAGLN expression was found to be downregulated in breast ductal carcinoma." (PMID 36523769, 2022).
cervical cancer (1 paper, 2019). A primary or metastatic malignant neoplasm involving the cervix. "In contrast to HPV-negative HNSC samples, HPV-positive tumors showed the same tendency as cervical cancers with respect to the expression of COL5A, MMP2, CLDN7, TAGLN, and AURKB, supporting their possible contribution to virus-induced carcinogenesis." (PMID 30918060, 2019).
Chronic constipation (1 paper, 2025). Constipation for longer than three months with fewer than 3 bowel movements per week, straining, lumpy or hard stools, and a sensation of anorectal obstruction or incomplete defecation. "Deg-AZM ameliorates chronic constipation by functioning as a Transgelin agonist that biomechanically promotes actin polymerization, thereby enhancing stress fiber bundle formation in intestinal smooth muscle cells." (PMID 41007743, 2025).
Cirrhosis (1 paper, 2023). A chronic disorder of the liver in which liver tissue becomes scarred and is partially replaced by regenerative nodules and fibrotic tissue resulting in loss of liver function. "Hence, Whether TAGLN participate in cirrhosis via activating monocyte and CD4 T cell to achieve matrix remodeling and migration, as well as cell differentiation and invasion needs further investigation." (PMID 36725885, 2023). "Our further investigation into the association between these DEGs and immune infiltration also revealed the correlations between ACTB, TAGLN, VIM, SOX9 and immune cells, supporting that these genes play a vital role in cirrhosis via regulating immune infiltration." (PMID 36725885, 2023).
colorectal polyp (1 paper, 2023). "The present study's findings suggest that the expression pattern of CDC42, TAGLN, and GSN genes was significantly increased during the transformation of normal tissue to polyp lesions, indicating their potential as prognostic biomarkers for colorectal polyp development." (PMID 37365287, 2023).
colorectal tumors (1 paper, 2020). "In human colorectal tumors, two other sub-populations of CAFs were reported based on their transcriptome, CAF-A, rich in MMP2, αFAP and COL1A2 (type 1 collagen α−chain 2) mRNA, and CAF-B, rich in α-SMA, PDGF-A and TAGLN (transgelin) mRNA, but their function was not determined." (PMID 33114328, 2020).
depression (1 paper, 2023). "Moreover, angiogenesis may be a possible link between TAGLN and depression." (PMID 38111702, 2023).
distal hereditary motor neuropathy type 2 (1 paper, 2024). "KCNMB1, MYH11, PNPLA2, and TAGLN linked to Distal Hereditary Motor Neuropathy type 2." (PMID 39480826, 2024). "We propose that KCNMB1, MYH11, TAGLN, and PNPLA2 are novel genes in Distal Hereditary Motor Neuropathy type 2." (PMID 39480826, 2024).
endometrial stromal tumor (1 paper, 2026). Neoplasms of the endometrial stroma that sometimes involve the myometrium. "IMT typically expresses smooth muscle markers (desmin, SMA, caldesmon, transgelin) and stromal markers (CD10, IFITM1), which can lead to misdiagnosis as leiomyoma or endometrial stromal tumor." (PMID 41560086, 2026).
endothelial dysfunction (1 paper, 2021). In vascular diseases, endothelial dysfunction is a systemic pathological state of the endothelium (the inner lining of blood vessels) and can be broadly defined as an imbalance between vasodilating and vasoconstricting substances produced by (or acting on) the endothelium. "The higher expression of TAGLN might be related to the hyperproliferative phenotype of CTEPH-ECs and it might have an important role in endothelial dysfunction." (PMID 33692478, 2021).
focal segmental glomerulosclerosis (1 paper, 2020). A renal disorder characterized by sclerotic lesions in the glomeruli. "Transgelin is expressed and distributed abnormally in kidney tissue in the contexts of MCNS, focal segmental glomerulosclerosis (FSGS), and membranous nephropathy (MN)." (PMID 32583562, 2020).
gastric adenocarcinoma (1 paper, 2019). "Furthermore, transgelin was introduced as a potential novel marker for gastric adenocarcinoma based on proteomics technology." (PMID 31391093, 2019). "In a comparative proteomics-based study on the gastric adenocarcinoma (GA) and paired non-neoplastic mucosa tissues, one of the upregulated proteins identified in GA was transgelin which was validated by immunohistochemistry and western blotting methods." (PMID 31391093, 2019).
gastric ulcer (1 paper, 2019). An ulcerated lesion in the mucosal surface of the stomach. "Transgelin is another protein that was overexpressed in gastric ulcer group." (PMID 31391093, 2019).
Holt-Oram syndrome (1 paper, 2024). Holt-Oram syndrome (HOS) is the most common form of heart-hand syndrome and is characterized by skeletal abnormalities of the upper limbs and mild-to-severe congenital cardiac defects. "The gene ontologies for list 4+ linked FOXF1, MYH11, and TAGLN to Holt-Oram Syndrome." (PMID 39480826, 2024). "We propose that FOXF1, MYH11, and TAGLN are novel genes in Holt-Oram Syndrome." (PMID 39480826, 2024).
Hyperglycemia (1 paper, 2025). An increased concentration of glucose in the blood. "Smad3 activation under hyperglycemia disrupts cytoskeleton via transgelin and caspase-3, leading to podocyte damage." (PMID 41009556, 2025).
hypertension nephropathy (1 paper, 2013). "In order to explore whether the expression of transgelin in periglomerular fibroblasts represents a general feature of renal pathology during the development of fibrosis, we decided to compare the UUO model and the hypertension nephropathy model in mice." (PMID 23840546, 2013).
hypertrophic cardiomyopathy (1 paper, 2023). A condition in which the myocardium is hypertrophied without an obvious cause. "In adjacent normal tissues, TAGLN and co-expressed genes are involved in KEGG pathways such as 'focal adhesion', 'hypertrophic cardiomyopathy', and 'tight junction'." (PMID 37365287, 2023).
leiomyosarcoma (1 paper, 2018). An uncommon, aggressive malignant smooth muscle neoplasm, usually occurring in post-menopausal women. "A previous report found that TAGLN was specifically expressed in 154 of 184 leiomyosarcoma (LMS) (84%) and could be used as a novel diagnosis marker for tumor of smooth muscle differentiation, especially for LMS." (PMID 30680066, 2018).
liver cancer (1 paper, 2021). An epithelial or non-epithelial malignant neoplasm that arises from the liver. "Molecular docking revealed the binding of JS-K to TAGLN and shTAGLN-2.15 cells were resistant to JS-K cytotoxicity, suggesting that TAGLN could be an important target in JS-K anti-HBV-positive liver cancer cells." (PMID 34001947, 2021). "TAGLN could be an important target in JS-K anti-HBV-positive liver cancer cells." (PMID 34001947, 2021).
liver cirrhosis (1 paper, 2023). "In summary, we found ACTB, TAGLN, VIM and SOX9 are the potential key biomarkers of liver cirrhosis." (PMID 36725885, 2023).
mucinous carcinomas (1 paper, 2013). "TAGLN levels were higher in undifferentiated tumors (poorly differentiated adenocarcinomas, signet ring cell carcinomas and mucinous carcinomas) than that in differentiated ones (well and moderate adnocarcinomas) (P = 0.003)." (PMID 23510049, 2013).